CAV2 (caveolin 2)
Description:
May act as a scaffolding protein within caveolar membranes. Interacts directly with G protein alpha subunits and can functionally regulate their activity. Acts as an accessory protein in conjunction with CAV1 in targeting to lipid rafts and driving caveolae formation. The Ser-36 phosphorylated form has a role in modulating mitosis in endothelial cells. Positive regulator of cellular mitogenesis of the MAPK signaling pathway. Required for the insulin-stimulated nuclear translocation and activation of MAPK1 and STAT3, and the subsequent regulation of cell cycle progression (By similarity).
Synonyms: CAV
Tractability: Antibody: its Gene Ontology location is reachable by antibodies, with high confidence; UniProt places it where antibodies can reach, with medium confidence. PROTAC: ubiquitination databases record sites on it; its protein half-life has been measured.
Gene: Protein-coding gene on chromosome 7 (116,287,380 to 116,508,541, forward strand). Ensembl gene ENSG00000105971.
Subcellular location: Nucleus; Cytoplasm; Golgi apparatus membrane; Cell membrane; Membrane, caveola
Subcellular location (Human Protein Atlas): Vesicles
Pathways (Reactome):
Signal Transduction: Extra-nuclear estrogen signaling
Gene Ontology:
Molecular function: heterotrimeric G-protein binding; protein binding; protein homodimerization activity; molecular adaptor activity; protein kinase binding; protein heterodimerization activity; protein-macromolecule adaptor activity; scaffold protein binding
Biological process: caveola assembly; G protein-coupled receptor signaling pathway; host-mediated activation of viral process; insulin receptor signaling pathway; positive regulation of dopamine receptor signaling pathway; positive regulation of MAPK cascade; receptor-mediated endocytosis of virus by host cell; regulation of mitotic nuclear division; vesicle fusion; vesicle organization; viral release from host cell; cell differentiation; endoplasmic reticulum organization; mitochondrion organization; negative regulation of endothelial cell proliferation; regulation of cytosolic calcium ion concentration; skeletal muscle fiber development
Cellular component: caveola; cytoplasmic vesicle; focal adhesion; membrane raft; perinuclear region of cytoplasm; plasma membrane; plasma membrane raft; protein-containing complex; transport vesicle; Golgi apparatus; sarcolemma; acrosomal membrane; caveolar macromolecular signaling complex; cytoplasm; Golgi membrane; membrane; nucleus
Genetic constraint (gnomAD): Loss-of-function variants: 7 observed, 14.02 expected, observed/expected ratio (o/e) 0.5, 90% interval 0.28 to 0.94. The upper end of that interval is the gene's LOEUF score, 0.94, which puts it in group 3 of 6, group 1 being the genes least tolerant of losing a copy. Missense variants: 221 observed, 208.51 expected, observed/expected ratio (o/e) 1.06, 90% interval 0.95 to 1.18. Synonymous variants: 73 observed, 85.96 expected, observed/expected ratio (o/e) 0.85, 90% interval 0.7 to 1.03.
Gene-disease validity (ClinGen):
ClinGen rates the evidence that CAV2 causes each of these diseases.
amyotrophic lateral sclerosis (autosomal dominant): Limited. Amyotrophic lateral sclerosis (ALS) is a neurodegenerative disease characterized by progressive muscular paralysis reflecting degeneration of motor neurons in the primary motor cortex, corticospinal tracts, brainstem and spinal cord.
Homologues: Orthologues: chimpanzee CAV2 (100% identical), macaque CAV2 (98% identical), mouse Cav2 (90% identical), pig CAV2 (88% identical), rabbit CAV2 (88% identical), dog CAV2 (80% identical), rat Cav2 (80% identical), tropical clawed frog cav2 (66% identical), zebrafish cav2 (51% identical), Caenorhabditis elegans cav-2 (33% identical), Caenorhabditis elegans cav-1 (23% identical). Paralogues in human: CAV1 (33% identical), CAV3 (31% identical).
Diseases named in the same sentence as CAV2 in open-access papers:
CAV2 is named in the same sentence as 104 diseases in open-access papers, as found by Europe PMC text mining. Sharing a sentence is not in itself a finding about the gene and the disease. The quoted sentences say what the papers report.
breast carcinoma (27 papers, 2004 to 2025). "In patients with breast cancer, both cav-1 and cav-2 are linked to basal-like tumors and those that lack positive steroid hormone receptor expression (triple-negative phenotype)." (PMID 39857963, 2025). "For example, CAV2 can promote renal cell carcinoma progression by influencing the EGFR/PI3K/Akt pathway 1 and CAV2 is associated with basal-like breast carcinoma and its poor prognosis." (PMID 35517414, 2022). "Cav-2 expression was also closely associated with basal-like immunophenotype and proved by univariate analysis to be a prognostic factor of breast cancer." (PMID 22229094, 2011). "Taken together, these data suggest that expression of CAV1 and CAV2 is associated with basal-like phenotype in breast cancer." (PMID 18612310, 2008). "In conclusion, our findings and those of other recently reported studies show that CAV1 and CAV2 have oncogenic properties and are associated with breast carcinomas of basal-like and triple negative phenotypes." (PMID 18612310, 2008). "The mechanism underlying the expression of CAV1 and CAV2 in breast cancer and specifically the basal-like phenotype is yet to be determined." (PMID 18612310, 2008). "Studies have shown that with the progression of breast cancer, the positive rate of Cav-3 in epithelial tissues decreases, while the positive rate of Cav-2 in interstitial tissues increases." (PMID 37828916, 2023). "(B) KM plotter analysis of EHD2, CAV1 and CAV2 overexpression correlation with relapse-free survival (RFS) for upper vs. lower quartiles in basal-like breast cancer (PAM50-based) cohorts of TCGA, GEO, and GEA datasets." (PMID 36625722, 2023). "For example, the hypermethylation of CGI silences the CAV2 gene, which can be used as an obvious marker of breast cancer." (PMID 35178391, 2022). "Subsequently, although CAV2 expression was observed in only 5.9% of breast cancers, the expression of this protein was found to have a prognostic impact on survival." (PMID 36114176, 2022). "Studies have confirmed that compared with the corresponding normal tissues, the mRNA level of CAV2 in human breast cancer tissues is significantly down-regulated (p < 0.001)." (PMID 35178391, 2022). "CAV1 and CAV2 also elucidated independent predicting value in the RFS of ER+ breast cancer patients, but the prognosis of breast cancer patients with other receptor status was not well differentiated by expression levels of CAV1 and CAV2." (PMID 34513683, 2021). "In a previous study, MiR-199a-3p contributed to breast cancer progression; whereas, Cav-2 repressed cancer progression." (PMID 31759347, 2019). "CAV2 was a major component of the inner surface of caveolae, and the expression of CAV2 was necessary for the control of E2‐dependent cellular proliferation in breast cancer." (PMID 28796930, 2017). "In breast carcinoma, caveolin-2 expression is frequently upregulated and correlates with poor prognostic status." (PMID 25623282, 2015). "As expected, epithelial genes known to be inactivated during EMT in breast cancer cells, such as Cdh1 (E-cadherin), Ocln (Occludin), Epcam, Cldn7 (Claudin 7), Id1, Krt7, Esr1, Cav2, Dsp, Gata3, and Cadm1 were among the downregulated genes." (PMID 25674539, 2015). "We have also previously shown that the level of expression of CAV- 1, CAV-2 and EphA2 protein correlated with sensitivity to dasatinib in breast cancer cell lines." (PMID 25594008, 2014). "CAV2 positive breast cancers frequently expressed basal markers, including Ck 5/6, Ck 14, p63 (P<0.001, 0.001 and <0.001, respectively)." (PMID 18612310, 2008). "This study highlights the link between CAV1 and CAV2 with the myoepithelial/basal- and triple-negative groups of breast cancer." (PMID 18612310, 2008). "Another gene that negatively correlated with NEP expression was caveolin 2, the expression of which is decreased in breast cancer tissue when compared to normal tissue and is correlated with hormone receptor status." (PMID 17207277, 2007).
breast carcinoma (continued). "CAV1 and CAV2 protein levels were downregulated in four representative breast cancer tissues compared to corresponding normal breast tissues." (PMID 15305200, 2004). "Results showed higher HER2/neu mRMA levels and lower CAV1 and CAV2 mRMA levels in breast cancer tissues than in corresponding normal tissues (P<0.001)." (PMID 15305200, 2004). "Caveolin-1 and -2 (CAV1, CAV2) are closely linked genes localised to the fragile region of 7q31 (FRA7G), and loss of heterozygosity involving this region has been reported in breast cancer." (PMID 15305200, 2004). "Paradoxically, it may support growth in some breast cancer lines by targeting caveolin-2, though caveolin-2 overexpression can reverse these effects." (PMID 41154751, 2025). "The Cav proteins include Cav-1, Cav-2 and Cav-3, among which Cav-1 has attracted the most attention as a tumor suppressor and promoting factor affecting the proliferation, apoptosis, migration, invasion and metastasis of breast cancer cells." (PMID 37828916, 2023). "Therefore, Cav-2, Cav-3 and Cav-1 can also act as related regulatory factors in breast cancer progression and play dual roles in cancer inhibition and promotion." (PMID 37828916, 2023). "Earlier research suggested that CAV2 levels are inversely correlated with breast cancer tumor size and that CAV2 may function as a tumor suppressor." (PMID 36114176, 2022). "Finally, both syndecan-2 and caveolin-2 were upregulated in tissue arrays from breast cancer patients compared to normal mammary tissue." (PMID 25623282, 2015). "To determine whether syndecan-2 and caveolin-2 expression correlates with disease and clinical outcome in breast cancer patients, we performed immunohistochemical analysis of human breast tissue microarrays." (PMID 25623282, 2015). "Caveolin-1 and CAV2 expression was observed in 13.4 and 5.9% of all breast cancer, respectively." (PMID 18612310, 2008). "Recently, it has been reported an strong association between CAV1 and CAV2 expression and high histological grade, and lack of hormone receptors positivity (ER and PR) in basal-like breast cancer subtype, providing evidence that these proteins can have oncogenic properties." (PMID 24591761, 2014). "Therefore, CAV1 and CAV2 play an important role in tumour progression in breast cancer patients." (PMID 15305200, 2004). "Our study also found that CAV2 and GSN were down-regulated in breast cancer, which is consistent with the results of previous studies." (PMID 35178391, 2022). "We see that all hypermethylated probes are significantly negatively correlated with the down-regulated CAV2 and GSN in breast cancer." (PMID 35178391, 2022). "Results elucidated that expression levels of CAV1, CAV2, CAVIN1, CAVIN2, and CAVIN3 were significantly lower in breast cancer tissues than in normal samples, while the expression level of CAVIN2 was correlated with advanced tumor stage." (PMID 34513683, 2021). "The statistical results showed that CAV1, CAV2, CAV3, CAVIN1, and CAVIN2 were significantly less expressed in breast cancer tissues than in normal ones." (PMID 34513683, 2021). "Comparatively, CAV2 and CAV3 were less studied in cancer, but CAV3 have showed a better potential in correlating to breast cancer development." (PMID 34513683, 2021). "The results elucidated that the transcriptional levels of CAV1, CAV2, CAVIN1, CAVIN2, and CAVIN3 were significantly lower in breast cancer tissues than in normal samples." (PMID 34513683, 2021). "Except for Cav-1, Cav-2 is also reported as a target of mi-RNAs in MDA-MB-231 and MT-1 breast cancer cell lines." (PMID 31759347, 2019). "MiR-199a-3p promotes cell proliferation and survival in MDA-MB-231, MT-1 breast cancer cells, and YPEN-1 endothelial cells lines by inhibiting endogenous and exogenous Cav-2." (PMID 31759347, 2019).
breast carcinoma (continued). "Our results indicated that CAV1 suppression correlated closely with that of CAV2 in breast cancer, that CAV1 level was inversely correlated with tumour size, and that CAV1 and CAV2 levels were correlated with hormonal receptor status." (PMID 15305200, 2004). "We then evaluated for correlations between CAV1, CAV2 and HER2/neu gene expression and clinicopathologic factors in the 162 breast cancer cases." (PMID 15305200, 2004). "In the present study, we investigated the mRNA levels of CAV1, Caveolin-2 (CAV2) and HER2/neu in breast cancer tissues from 162 cases by the real-time PCR to evaluate the clinical significance of these genes." (PMID 15305200, 2004). "In summery, our results indicated that CAV1 suppression correlated closely with that of CAV2 in breast cancer, that CAV1 level was inversely correlated with tumour size, and that CAV1 and CAV2 levels were correlated with hormonal receptor status." (PMID 15305200, 2004). "We examined quantitatively the mRNA levels of CAV1, CAV2 and HER2/neu in 162 cases of breast cancer using real-time PCR." (PMID 15305200, 2004). "In summary, our research has found two key genes (CAV2 and GSN) related to breast cancer that may be regulated by DNA methylation and discovered three DNA methylation probes (cg13569051, cg14399183, and cg25274503)." (PMID 35178391, 2022). "miR-222-3p can also trigger malignant transformation by altering the expression levels of genes involved in cell death and survival, such as CAV2, PTEN, FOXO3, CDK6 and promote aggressive ER-negative breast tumors by increasing proliferation and migratory activity of breast cancer cells." (PMID 27833082, 2016). "Our patient tissue microarray data showed that syndecan-2 expression and caveolin-2 were significantly increased in breast cancer patients regardless of tumor grade." (PMID 25623282, 2015). "On univariate analysis only CAV2 had a prognostic impact on breast cancer-specific survival; however, this was not independent from other traditional markers on multivariate analysis." (PMID 18612310, 2008). "However, in previous studies on breast cancer, there was almost no discovery of the relationship between the DNA methylation of cg25274503 and CAV2 expression and the DNA methylation of cg13569051 and cg14399183 and the GSN expression." (PMID 35178391, 2022). "Moreover, a PCR study suggested downregulation of CAV1 and CAV2 mRNA levels in non-microdissected breast cancer." (PMID 18612310, 2008). "Our study confirmed that mRNA level of CAV1 and CAV2 were significantly downregulated in human breast cancer tissues compared to corresponding normal tissues (P<0.001), and that CAV1 and CAV2 mRNA levels were significantly correlated with each other in breast cancer cell lines and tissues." (PMID 15305200, 2004).
glaucoma (20 papers, 2011 to 2024). Increased pressure in the eyeball due to obstruction of the outflow of aqueous humor. "Results from a genome-wide association study have suggested that the CAV1/CAV2 locus is associated with glaucoma, but this association and its potential underlying mechanisms need to be confirmed and further explored." (PMID 28878269, 2017). "This gene codes for a component of a membrane complex involved in vesicular trafficking process, a function similar to that of the Caveolin genes (CAV1 and CAV2) which have previously been associated with primary open-angle glaucoma." (PMID 24518671, 2014). "Common sequence variants near CAV1 (caveolin 1) and CAV2, two of the genes only associated with focal adhesions, were recently reported to be associated with primary open-angle glaucoma." (PMID 22312193, 2012). "Given the recent association study results, CAV1 and CAV2 have been implicated in glaucoma pathogenesis." (PMID 21321670, 2011). "The mechanism by which defects in either CAV1 or CAV2 might cause glaucoma is unknown, but it has been hypothesized that such mutations might lead to glaucoma by altering nitric oxide or transforming growth factor-β (TGF-β) signal transduction." (PMID 21321670, 2011). "However, these expression data do provide some support to the hypothesis that variants in CAV1 or CAV2 may be the source of glaucoma risk mapped to chromosome 7q31." (PMID 21321670, 2011). "Genes with type-specific RGC expression patterns included the glaucoma-associated genes SIX6, which was enriched in midget ganglion cells; CAV2 and POU6F2 enriched in ON parasol RGCs and AFAP1, enriched in peripheral ON parasol RGCs." (PMID 32555229, 2020). "Sequence tags from 2 recently identified glaucoma-related genes, lysyl oxidase 1 (LOXL1; associated with exfoliation glaucoma), and caveolin 1 and caveolin 2 (associated with POAG) were expressed in at least two libraries." (PMID 21528004, 2011). "Like most candidates found associated with diseases in GWAS, the association, function and mechanism of CAV1/CAV2 in glaucoma have not yet been fully explored." (PMID 28878269, 2017). "Having said that, no glaucoma-causing mutations have been identified either in CAV1 or CAV2 to date." (PMID 22876122, 2012). "CAV-1 and CAV-2 are expressed in normal and glaucoma tissue and TM cell lines." (PMID 22128235, 2011). "The chromosome 7q31 locus is tagged by the minor allele of rs4236601 and contains two genes, CAV1 and CAV2, although no glaucoma-associated mutations in these genes have been found to date." (PMID 21321670, 2011). "Further studies are required to reveal whether the variability in CAV-2 expression is relevant to glaucoma pathogenesis." (PMID 22128235, 2011). "Although no glaucoma-causing mutations have been identified in either CAV1 or CAV2 to date, the results of the recent genome-wide association study suggests their existence." (PMID 21321670, 2011). "Furthermore, nsSNP rs8940 has previously been annotated in the coding region of CAV2 in Australian and Swedish glaucoma patients, but its association with POAG was not significant after adjusting for the effects of a correlated (LD r2 = 0.63) SNP rs4236601." (PMID 35741817, 2022). "The goal of this study was to investigate the expression and regulation of caveolin 1 (CAV-1) and caveolin 2 (CAV-2) in normal and glaucoma trabecular meshwork (TM) cells." (PMID 22128235, 2011). "Expression in human retina and tissues of the aqueous humor outflow pathway does not prove that either caveolin 1 or caveolin 2 has a role in glaucoma pathogenesis." (PMID 21321670, 2011).